CRP (C-reactive protein)
Diseases named in the same sentence as CRP in open-access papers (continued):
Sharing a sentence is not in itself a finding about the gene and the disease.
Obesity (continued). "Higher levels of glycosylated Hb, CRP, IL-6, and fibrinogen, obesity, waist circumference, presence of hypertension grade 2, and AF were significantly related to poor general health in the total sample." (PMID 26121035, 2015). "The two main findings are the negative impact of dyslipidemia, further worsened if hypertension and or obesity coexist, and inflammation markers (CRP and IL-6) on TL maintenance." (PMID 25799396, 2015). "Blood pressure (BP), plasma concentrations of glucose, TC, TG, CRP levels, BMI and the prevalence of overweight and obesity were significantly higher, while HDL-c levels were significantly lower in the case group than those of the control group." (PMID 26209006, 2015). "Of the obese subjects, 76.3% had >219 pg/ml CRP in their saliva, indicating that the inflammatory state was the most common form of obesity." (PMID 24915044, 2014). "By contrast, whilst obesity is one of the strongest determinants of CRP levels, the exact mechanism linking obesity and inflammation remains to be elucidated." (PMID 24944619, 2014). "In the unadjusted model, each 1 ng/dL increase in A-FABP increased the probability of MetS by 5.7%, HOMA-IR ≥ 3.4 by 3.7%, hypertension by 3.5%, HDL-C < 50 mg/dL by 17%, TC/HDL-C ≥ 4 by 8.3%, TG/HDL-C ≥ 1.3 by 4%, CRP ≥ 1.0 by 9.1%, and obesity by 18%." (PMID 24971341, 2014). "In a cross-sectional analysis from the United States, where the prevalence of overweight and obesity in children and adolescents is higher, a relationship between adiposity and increasing CRP was observed from 3 years of age." (PMID 24603645, 2014). "Obesity-related inflammation increases plasma levels of many acute-phase proteins such as C-reactive protein (CRP), hepcidin, and several cytokines." (PMID 24764731, 2014). "For example, the levels of circulating fibrinogen and other acute phase reactants, including TNF, IL-6, and C-reactive protein (CRP) were found to be elevated in obesity." (PMID 25309773, 2014). "Obesity is often associated with increased markers of inflammation, in part because adipocytes themselves release adipokines, including IL‐6, TNF‐α, and CRP." (PMID 25347862, 2014). "Overweight/obese women without clustering of cardiometabolic risk factors possess abnormal levels of inflammatory markers including CRP and fibrinogen suggesting that obesity represents a chronic inflammatory state." (PMID 24957141, 2014). "A socioeconomic gradient in white matter tract integrity has been demonstrated, partly mediated by obesity, smoking, and C-reactive protein, suggesting inflammation as a key mediating pathway." (PMID 24558456, 2014). "Raised plasma CRP concentrations have been shown to be associated with aging, smoking, low HDL cholesterol level, and obesity." (PMID 24955583, 2014). "Adiponectin levels are lower in subjects with obesity and type 2 diabetes; leptin and c-reactive protein correlate positively with body mass index, insulin resistance and diabetes." (PMID 25208549, 2014). "The distinct behaviors of PTX3 compared with those of CRP also suggest that long and short pentraxins have different relationships with the pathogenesis of obesity and metabolic syndrome." (PMID 24705587, 2014). "Obesity is associated with a low-grade chronic systemic inflammation and in particularly interleukin-6 (IL-6), TNF-α and C-reactive protein (CRP) are present at high levels in the serum of obese people." (PMID 25386150, 2014). "Mean alanine transaminase, high sensitive C-reactive protein level, interventricular septum thickness and left ventricular mass were statistically higher in obesity groups when compared with the controls." (PMID 25755863, 2014). "Increased levels of acute-phase proteins such as C-reactive protein (CRP) have been reported in obesity-related inflammation." (PMID 24764731, 2014).
Obesity (continued). "Findings: Weight, body mass index, waist circumference, insulin, alanine transaminase, and high sensitive C-reactive protein values were markedly higher in obesity group when compared with controls (P<0.001)." (PMID 25755863, 2014). "In our study, high sensitive C-reactive protein levels, the marker of inflammatory response, were increased markedly in obesity and MS groups." (PMID 25755863, 2014). "We have identified four salivary biomarkers in 10-year old subjects that change significantly with increasing obesity; insulin, CRP, adiponectin and leptin." (PMID 24915044, 2014). "Therefore, CRP-mfs might be used as an obesity-associated inflammatory marker." (PMID 25299074, 2014). "Secondly, it is well known that adiposity is a major predictor of CRP, and we found that the prevalence of obesity was higher among women than among men (47.56% versus 29.53%)." (PMID 25309988, 2014). "Among black adults, residing in the most deprived neighborhoods was associated with increased odds of obesity (p < .01), lower HDL (p < .001), high blood pressure (p < .01), elevated fasting glucose (p < .001), inflammation (p < .01), and CRP-MetS (p < .001)." (PMID 25539758, 2014). "For example, among all metabolic alterations considered, it is known that obesity is a major predictor of CRP." (PMID 25309988, 2014). "The objective is to evaluate if there is an association between serum levels of CRP and endothelial function in women with overweight/obesity, as well as the correlation between CRP and anthropometric variables." (PMID 23864919, 2013). "We tried to minimize the potential confounding by obesity and inflammation controlling for BMI and oxidative and inflammatory status (CRP, adiponectin, oxLDL) in the multivariate models." (PMID 24167545, 2013). "The size of the effects of the obesity categories is reduced on the 8-indicator summary measure in both England and the US, indicating the strong link between CRP and obesity." (PMID 23781331, 2013). "The obesity panel in serum required a 1∶500 dilution to bring CRP and adiponectin levels into the calibration range of the assay while no dilution was required for saliva samples." (PMID 23577067, 2013). "Obesity is proposed as a chronic low-grade proinflammatory state; alterations in CRP and proinflammatory cytokines such as TNF-α and IL-6 are commonly reported in obesity." (PMID 23826157, 2013). "Low adiponectin levels are inversely related to high levels of C-reactive protein (CRP) in patients with obesity, type 2 diabetes, and CVD." (PMID 23843680, 2013). "In conclusion, the results of this study highlight novel endocrine mechanisms involving the modulation of serum leptin and CRP concentrations by which chitosan exhibits anti-obesity properties in vivo." (PMID 23342013, 2013). "CRP, as an acute-phase protein which originates in the liver as well as adipose tissue, has many pathophysiologic roles in low-grade inflammation in obesity." (PMID 23617205, 2013). "For instance, the 81% increased risk for cardiovascular disease onset is very similar to that observed for well-established risk factors, such as obesity, metabolic syndrome, low high-density lipoprotein (HDL) cholesterol or high C-reactive protein (CRP)." (PMID 23672628, 2013). "Obesity was significantly more common among participants with elevated CRP in both RDD (χ2 test, P < 0.003; Cramer's V = 0.40) and control groups (χ2 test; P < 0.033; Cramer's V = 0.31)." (PMID 24170724, 2013). "Obesity and serum C-reactive protein (CRP) (a sensitive marker of inflammatory activity) are associated with most chronic diseases." (PMID 23391158, 2013). "The study included patients with overweight/obesity who had CRP and endothelial function tests already made and inserted into the survey database." (PMID 23864919, 2013). "Within the regulation of the inflammatory cascade, CRP suppresses adiponectin exaggerating to the inflammatory reaction in obesity." (PMID 24023413, 2013).
Obesity (continued). "Higher CRP levels have been reported in OSA patients, but it is difficult to tease out the independent contribution of obesity on the CRP levels." (PMID 23862060, 2013). "Obesity is a proinflammatory state, usually presenting a low-grade chronic inflammation, with increased levels of proinflammatory cytokines and C-reactive protein (CRP), that are positively related to the body mass index (BMI)." (PMID 24634792, 2013). "A recent study on obesity and survival after colon cancer (388 colon cancer patients) found that patients who had the highest amounts of serum CRP were significantly more likely to die of colon cancer (P ≤ 0.001)." (PMID 23819063, 2013). "Consistent with the chronic low-grade inflammatory state of obesity, elevated concentrations of interleukin-6 (IL-6) and C-reactive protein (CRP) have been observed in obese pregnant women." (PMID 23840945, 2013). "Prevalence of overweight, obesity, the metabolic syndrome, hs-CRP levels and IFG were significantly higher in cases than controls." (PMID 23326306, 2013). "C-reactive protein (CRP) and IL-6 are other biomarkers of systemic inflammation, which are increased in obesity." (PMID 24025484, 2013). "In parallel with the development of obesity, production of adipose tissue derived proteins, such as C-reactive protein (CRP), is usually increased." (PMID 23986778, 2013). "In general, overweight/obesity was associated with high blood pressure, high blood levels of fasting glucose, uric acid, triglyceride, high levels of ACR, and high blood levels of CRP." (PMID 24058515, 2013). "Among these, regression analysis found four well-established obesity associated genes that were positively correlated (CPE, LEP, NPY1R, and NPY5R), and two genes (APOM, and CRP) that were negatively correlated with weight gain." (PMID 23544116, 2013). "For example, hepatic C-reactive protein (CRP), which is increased in obesity, binds leptin and limits leptin receptor binding and transport across the BBB." (PMID 22518191, 2012). "The results suggest a strong association between poor cardio-respiratory fitness and/or overweight/obesity and inflammatory status in children, based on elevated salivary CRP levels." (PMID 23108518, 2012). "Patients with DM or obesity have increased circulating levels of inflammatory markers including C-reactive protein (CRP), tumour necrosis factor-alpha (TNF-α), interleukin-6 (IL-6), and ICAM-1." (PMID 22347666, 2012). "Elevated plasmatic CRP levels and reduced serum CFH associated with obesity, hypertension, and smoking are considerable risk factors for AMD." (PMID 22969267, 2012). "Poor cardio-respiratory fitness (OR 2.7, 95% CI: 1.2–6.1, p = 0.02) and overweight/obesity (BMI ≥ 85th percentile) (OR 2.5, 95% CI: 1.1–5.9, p = 0.03) were independent predictors of elevated salivary CRP secretion rate." (PMID 23108518, 2012). "Thus, CRP values >10 mg/L might indicate chronic inflammation in a large proportion of individuals, and this may especially be so in people with characteristics such as obesity and smoking, which are known risk factors for chronic inflammation." (PMID 22558327, 2012). "Inflammatory state of obesity is characterized by insulin resistance, increased serum concentrations of C-reactive protein, IL-6, IL-8, TNF-α, and so forth." (PMID 23091306, 2012). "The novelty of the results presented here is the association between the TT genotype of SNP rs1130864 with obesity and T2D and the haplotypes 2 (TGAG) and 7 (TGGG) with increase of CRP and BMI, respectively." (PMID 23049543, 2012). "Of the metabolic variables studied, adiposity, as measured by BMI and waist circumference, was the major predictor of hs-CRP (similar to results obtained from international studies), suggesting obesity as a mediator of excess CRP seen in the MetS." (PMID 29062730, 2012). "In obesity, the plasma level of C-reactive protein (CRP) is high, which is largely synthesized by the liver." (PMID 22891067, 2012).
Obesity (continued). "For example, elevated concentrations of C-reactive protein (CRP), an acute-phase inflammatory protein, indicate increased risk for obesity-associated disorders." (PMID 26486919, 2012). "More studies are needed to improve our understanding of the interrelations among cardiorespiratory fitness, CRP, and obesity in children." (PMID 22315623, 2012). "In consistent with our finding, it has been positively correlated human obesity with blood levels of CRP and Hp." (PMID 23283045, 2012). "The relationship between obesity and CRP levels in the children is limited, especially among the children younger than 12 years of age." (PMID 22691465, 2012). "There are evidences that demonstrate the fact that elevated CRP levels are closely related to obesity." (PMID 22649299, 2012). "Anthropometric measures of obesity and level of insulin resistance were highly correlated to the acute phase reactants CRP and fibrinogen; however, the degree of insulin resistance was not predicted by the pro- or anti-inflammatory cytokine markers." (PMID 22682228, 2012). "Accordingly, C-reactive protein has been considered a correlate of obesity in women with GDM, and the presence of inflammatory markers have been reported in women with pGDM and increased cIMT." (PMID 22651701, 2012). "Increased levels of IL-6, IL-1RA, sICAM-1 and E-selection in the “high” CRP group are reminiscent of subclinical systemic inflammation seen in obesity, metabolic syndrome or type 2 diabetes." (PMID 22448235, 2012). "Plasma C-reactive protein (CRP) is the obesity-related inflammatory marker that has been most consistently associated with cardiovascular risk." (PMID 21246032, 2011). "Hs-CRP levels correlated positively and significantly with smoking duration, but only after adjustment for age and obesity markers (BMI, WC)." (PMID 21298201, 2011). "Low adiponectin levels are inversely related to high levels of C-reactive protein (CRP) in patients with obesity, type 2 diabetes, and CAD." (PMID 21941676, 2011). "Increased levels of activated plasminogen activator inhibitor 1 (aPAI-1), tumor necrosis factor-alpha (TNFα), C-reactive protein (CRP), as well as other conditions such as obesity and the MetS, are now considered low-grade inflammatory states." (PMID 21483749, 2011). "IL-6, CRP, and TNF-α are the main inflammatory molecules associated with obesity-related inflammation." (PMID 21599899, 2011). "In conclusion, the present study evidenced a clear inverse association of IGF-I status with FM, spleen enlargement, CRP and HS, adding new information on the complex relationships between impaired IGF-I status, HS, inflammation, and obesity." (PMID 21846339, 2011). "Obesity reflects ageneralized proinflammatory state with its increased inflammatorymarkers like C reactive protein, IL-6, IL-8, IL-10, PAI-1,TNF-α, and hepatocyte growth factor." (PMID 21991518, 2011). "Obesity represents a chronic state of inflammation, with increased levels of the C-reactive protein (CRP) and decreased levels of adiponectin." (PMID 21548919, 2011). "CRP has a number of roles in several cardiovascular diseases, and levels of CRP are positively correlated with obesity and insulin resistance." (PMID 20847810, 2010). "Data on the influence of socioeconomic indicators on CRP levels is very limited (especially outside high-income countries), but findings with respect to obesity have been described." (PMID 20137842, 2010). "Risk factors with ICU admission were older age, long duration of symptoms, asthma, obesity, abnormalities of chest radiography, leukocytosis and higher CRP." (PMID 20979619, 2010). "Previous studies that examined the relationships among insulin resistance, CRP, and obesity were inconsistent." (PMID 21167068, 2010). "In women, CRP and fibrinogen both clustered with the first factor, labelled "obesity"; whereas in men, CRP clustered with obesity whilst fibrinogen (with CRP) clustered with HbA1c/ACR, labelled "metabolic"." (PMID 21029470, 2010).
Obesity (continued). "If BMI were used as the measure of obesity in the multivariate model, population remained as a significant determinant of CRP in women (OR for DRUID relative to AusDiab 1.47, 95%CI 1.01-2.13), but not for men (OR 1.28, 95%CI 0.85-1.94)." (PMID 21078191, 2010). "In this community-based study, we demonstrated that all obesity indicators, except WHR in men, were strongly associated with a high CRP level in Taiwanese men and women when sociodemographic factors and lifestyle behaviors were considered." (PMID 20875142, 2010). "With respect to CHD and biomarkers of inflammation, higher levels of CRP have been shown even among children who have higher levels of 'classical' risk factors for CHD, such as obesity." (PMID 20070881, 2010). "It is additionally known that obesity provokes systemic inflammation, leading to the development of metabolic syndrome, insulin resistance and high levels of CRP." (PMID 20949085, 2010). "The relationships between obesity indicators and a high level of hs-CRP were examined using multivariate logistic regression analysis." (PMID 20875142, 2010). "Leptin correlated positively with obesity, glucose metabolism, lipid profile, hepatic function and C-reactive protein, and negatively with HDL and Apolipoprotein A-I/B ratio." (PMID 20537155, 2010). "Risk factors of ICU admission were older age, long duration of symptoms, asthma, obesity, abnormalities of chest radiography, leukocytosis and higher CRP." (PMID 20979619, 2010). "With increasing obesity, mean CRP levels increased more steeply for DRUID women than for other groups." (PMID 21078191, 2010). "Evidence supports an inverse association between physical fitness and several risk factors for PE, including glucose intolerance, hypercholesterolemia, high blood pressure, obesity, and markers of systemic inflammation like C-Reactive Protein (CRP)." (PMID 19919718, 2009). "In conclusion, we found that high plasma calprotectin levels were a marker of obesity independently of classical inflammation markers such as CRP, TNF-α and circulating neutrophil number." (PMID 19823685, 2009). "The association between serum CRP and CIMT attenuated towards the null in adjustments for obesity and other risk factors and this is consistent with several previous studies." (PMID 18714381, 2008). "In our study CRP contributes a small fraction to the obesity factor (a loading of 0.35) and less to the lipids factors (a loading of 0.14)." (PMID 18154661, 2007). "Circulating CRP levels are suggested to relate to adipose derived mediators such as leptin and TNFα, and positively correlate with measures of obesity in otherwise healthy adults." (PMID 16965635, 2006). "However, other components of the immune system are also affected, as the number of white blood cells is increased in people with obesity and concentrations of C-reactive protein (CRP) produced by the liver are increased." (PMID 41503519, 2026). "Subsequent mediation analysis revealed that HOMA‐IR, not CRP, significantly mediated the association between irisin, obesity and sarcopenic obesity." (PMID 41457869, 2026). "Furthermore, our finding that associations between irisin and obesity were attenuated after adjustment for HOMA‐IR and CRP suggests that these relationships are mediated through insulin resistance and inflammatory pathways." (PMID 41457869, 2026). "In addition, CRP is easily disturbed by metabolic factors such as obesity and hyperlipidemia, resulting in poor specificity; IL-6 has a short half-life and the blood concentration fluctuates greatly, so it is not easy to grasp the timing of detection." (PMID 41517734, 2026). "Biomarkers like leptin, adiponectin, and CRP can identify nonresponders to treatments, high‐risk patients, and specific obesity‐related complications, guiding individualized therapeutic strategies." (PMID 40551726, 2025).